DFFB (DNA fragmentation factor subunit beta)
Description:
Nuclease that induces DNA fragmentation and chromatin condensation during apoptosis. Degrades naked DNA and induces apoptotic morphology.
Synonyms: CAD; CPAN; DFF-40; DFF2; DFF40
Tractability: PROTAC: ubiquitination databases record sites on it; its protein half-life has been measured.
Gene: Protein-coding gene on chromosome 1 (3,857,267 to 3,885,429, forward strand). Ensembl gene ENSG00000169598.
Subcellular location: Cytoplasm; Nucleus
Subcellular location (Human Protein Atlas): Nucleoli; Nucleoplasm
Pathways (Reactome):
Programmed Cell Death: Apoptosis induced DNA fragmentation
Gene Ontology:
Molecular function: DNA nuclease activity; enzyme binding; identical protein binding; protein binding; DNA binding; DNA endonuclease activity; hydrolase activity; nuclease activity
Biological process: apoptotic chromosome condensation; apoptotic DNA fragmentation; DNA catabolic process; negative regulation of apoptotic DNA fragmentation; apoptotic process
Cellular component: chromatin; cytosol; nucleolus; nucleoplasm; nucleus; protein-containing complex; cytoplasm
Genetic constraint (gnomAD): Loss-of-function variants: 29 observed, 34.6 expected, observed/expected ratio (o/e) 0.84, 90% interval 0.62 to 1.14. The upper end of that interval is the gene's LOEUF score, 1.14, which puts it in group 5 of 6, group 1 being the genes least tolerant of losing a copy. Missense variants: 398 observed, 443.49 expected, observed/expected ratio (o/e) 0.9, 90% interval 0.83 to 0.98. Synonymous variants: 170 observed, 179.99 expected, observed/expected ratio (o/e) 0.94, 90% interval 0.83 to 1.07.
Homologues: Orthologues: chimpanzee DFFB (99% identical), macaque DFFB (90% identical), mouse Dffb (77% identical), rat Dffb (76% identical), pig DFFB (73% identical), guinea pig DFFB (64% identical), dog DFFB (63% identical), tropical clawed frog dffb (56% identical), zebrafish dffb (48% identical), Drosophila melanogaster Drep4 (30% identical).
Diseases named in the same sentence as DFFB in open-access papers:
DFFB is named in the same sentence as 23 diseases in open-access papers, as found by Europe PMC text mining. Sharing a sentence is not in itself a finding about the gene and the disease. The quoted sentences say what the papers report.
leukaemia (4 papers, 2015 to 2023). "Cumulatively, this data suggests that pro‐survival isoform switching of BCL2 family members together with DFFB isoform regulation may play a role in leukemia proliferation and survival and thus a potential therapeutic option with a pharmacological splicing modulatory compound." (PMID 36819185, 2023).
hepatocellular carcinoma (3 papers, 2003 to 2019). A malignant tumor that arises from hepatocytes. "However, aberrant DFFB transcripts resulting from splicing have been reported in hepatocellular carcinoma." (PMID 15475940, 2004).
glioblastoma (2 papers, 2018 to 2023). The most malignant astrocytic tumor (WHO grade IV). "DFFB have previously been described to play a role in persister cell mutagenesis and tumor relapse and its under‐expression have been reported in numerous malignancies such as endometrial malignancies and glioblastoma." (PMID 36819185, 2023).
neuroblastoma (2 papers, 2002 to 2004). Neuroblastoma (NB) is the most common solid, extracranial childhood tumor. "Recently, structure and mutation analysis of the gene encoding DFF40, DFFB, was performed in primary neuroblastoma tumours and cell-lines." (PMID 11870543, 2002). "No somatic mutations of DFFB were detected in 41 neuroblastomas examined." (PMID 15475940, 2004).
glaucoma (1 paper, 2013). Increased pressure in the eyeball due to obstruction of the outflow of aqueous humor.
kidney tumours (1 paper, 2009). "In fact, we found that in lung cancer over expression of BCL2 could be explained by the under expression of MIR15A, MIR16-1, and MIR16-2, while in kidney tumours over expression of DFFB, HTATIP and RELA could be related to the under expression of MIR124A-1, MIR124A-2, and MIR124A-3." (PMID 19402918, 2009).
oligodendroglioma (1 paper, 2005). A well-differentiated (WHO grade II), diffusely infiltrating neuroglial tumor, typically located in the cerebral hemispheres. "However, it is possible that DFFB haploinsufficiency from 1p allelic loss is a contributing factor in oligodendroglioma development." (PMID 16156899, 2005).
Sepsis (1 paper, 2025). Sepsis is defined as life-threatening organ dysfunction caused by a dysregulated host response to infection. "In contrast, 5′-A motifs, associated with the activity of the nuclease DNA Fragmentation Factor Subunit Beta (DFFB), were observed at lower frequencies in sepsis patients and were negatively correlated with bilirubin." (PMID 40795850, 2025).
tumor (11 papers, 2002 to 2025). "DFFB inhibition may also promote tumour immunity through the upregulation of immune-stimulating ISGs such as STING56 specifically within drug-stressed tumour cells." (PMID 41249572, 2025). "Moreover, DFFB deletion in tumor cells may attenuate killing by granzymes, as inactive DFFB is cleaved and activated by granzymes B and M. BAD/BAX deletions in tumor cells may also blunt rapid killing by granzyme B, which activates BAX and caspase-3." (PMID 41175874, 2025). "Thus, variation and deregulation of the DFFB gene in the presence of apoptosis-inducing drugs might have an impact on their efficiency in tumor cells." (PMID 30545124, 2018). "However, while DFFB WT tumours regrew during further treatment, DFFB KO tumours remained in a regressed state and failed to regrow." (PMID 40894800, 2025).
cancer (4 papers, 2003 to 2026). A tumor composed of atypical neoplastic, often pleomorphic cells that invade other tissues. "GWAS studies show that regulatory non-coding variants may play a role in multiple distinct diseases such as cancer and thus the other two intronic variants associated with response (rs2293194 in KCNAB1 and rs4376673 in DFFB) also represent a potential target for further studies." (PMID 30545124, 2018).
infection (1 paper, 2025). The state of being infected such as from the introduction of a foreign agent such as serum, vaccine, antigenic substance or organism. "It is tempting to speculate that this might relate to faulty trafficking and mislocalization of the main DNA fragmentation factor (DFFB) due to the NCTD during CVB3–2Awt infection." (PMID 40875754, 2025).
DFFB also shares sentences with these, for which no sentence is quoted: breast carcinoma (1 paper); colorectal cancer (1); endometrial cancer (1); endometrial tumors (1); epilepsy (1); Huntington disease (1); kidney cancer (1); lung carcinoma (1); lupus (1); melanoma (1); ovarian carcinoma (1); uterine leiomyosarcomas (1).